NCOA4 (nuclear receptor coactivator 4)
Diseases named in the same sentence as NCOA4 in open-access papers (continued):
Sharing a sentence is not in itself a finding about the gene and the disease.
cancer (74 papers, 2010 to 2025). A tumor composed of atypical neoplastic, often pleomorphic cells that invade other tissues. "It has been reported that cancer-associated fibroblasts upregulate the expression of NCOA4 in NK cells through the DIP2A-P38 pathway via a mechanism driven by cancer-associated fibroblast-derived FSTL1, leading to ferritinophagy and ferroptosis in NK cells." (PMID 40959272, 2025). "The dysregulation of NCOA4 is associated with several diseases, including neurodegenerative disorders and cancer, highlighting the NCOA4-ferritin interface as a prime target for drug development." (PMID 38714719, 2024). "With the use of a pan-cancer investigation of approximately 10,000 original tumors spanning 33 various cancer types, we observed that low levels of NCOA4 in malignancies were linked with poor overall survival." (PMID 35756082, 2022). "Then, using the heatmap, we analyzed the association between the top 10 genes and NCOA4 in 33 different forms of cancer." (PMID 35756082, 2022). "As a result, we sought to investigate the NCOA4 genetic variants using the cBioPortal (TCGA, Pan-Cancer Atlas)." (PMID 35756082, 2022). "NCOA4 has been proven to be a hallmark of ferritinophagy, which plays a key role in degenerative diseases and cancers." (PMID 33420375, 2021). "It promotes cell ferroptosis by degrading intracellular ferritin and causing iron retention, which indicates that NCOA4 is an important molecule in the process of ferroptosis in cancer." (PMID 33402128, 2021). "Among the affected genes, ETV1, CCDC6, and NCOA4 are causally implicated in cancer according to the Cancer Gene Census." (PMID 32580154, 2020). "Furthermore, C-MYC is implicated in reducing NCOA4-mediated ferroptosis, enhancing cancer cell invasion and immune evasion." (PMID 39403142, 2024). "All of above suggest that NCOA4 expression is associated with ferritinophagy in cancer cells." (PMID 38110359, 2023). "We discovered that low levels of NCOA4 in malignancies were associated with poor overall survival after conducting a pan-cancer examination including almost 10,000 original tumors spanning 33 different cancer types in a single study." (PMID 35756082, 2022). "Additionally, there were statistically significant associations between NCOA4 expression and OS in both cancer types." (PMID 35756082, 2022). "Iron (Fe2+) ferrous ions assay showed that when NCOA4 was overexpressed, cancer cells were more resistant to erastin-induced ferroptosis compared with only FTL overexpressed group." (PMID 41281761, 2025). "In contrast, cucurbitacin D has been reported to enhance ferritinophagy through NCOA4 activation, liberating stored ferritin-bound Fe2+ and amplifying lipid peroxidation, thus promoting ferroptotic stress in resistant cancer cells." (PMID 41228309, 2025). "Lipid peroxidation MDA assay also displayed that when NCOA4 was overexpressed, cancer cells had more resistance to erastin-induced ferroptosis compared with only FTL overexpressed group." (PMID 41281761, 2025). "Evidence shows that NCOA4 is required for iron-mediated cell death in certain cancer cell lines and MEF cells." (PMID 40788949, 2025). "In the model of clear cell renal cell carcinoma, it was noted a decreased expression of NCOA4 had an impact on high‐grade malignant tumours and advanced TNM staging." (PMID 38389491, 2024). "The main mode of iron released from ferritin is selective autophagy mediated by NCOA4, therefore, NCOA4-mediated ferritinophagy has a key role in cancer progression." (PMID 38110359, 2023). "NCOA4 not only facilitates cellular ferritinophagy but also plays a role in cancer cell-mediated immune responses." (PMID 38110359, 2023). "Studies have shown that lipopolysaccharide (LPS) can regulate ferritin conversion by inhibiting NCOA4 as a therapeutic target for cancer." (PMID 38110359, 2023).
cancer (continued). "For instance, the diminished expression of NCOA4 in renal clear cell carcinoma has been found to govern unfavorable cancer prognosis and impaired infiltration of immune cells." (PMID 38110359, 2023). "RET fusion-positive carcinomas were associated with aggressive disease, including frequent LNM and DM, especially in cases of NCOA4/RET-positive carcinomas, even in early-stage disease, and with increased rates in pediatric and adolescent patients." (PMID 37882481, 2023). "The current work conducted a comprehensive analysis of NCOA4 expression in a pan-cancer dataset for the first time." (PMID 35756082, 2022). "Until now, NCOA4 has only been explored in a few cancers, and therefore it is very important to clarify the regulatory and molecular mechanisms of NCOA4 in cancer progression and thus develop innovative therapeutic approaches for these diseases." (PMID 36552889, 2022). "From the pan-cancer study results above, we find that NCOA4 gene expression in COAD and KIRC was consistent with protein expression as determined by IHC staining." (PMID 35756082, 2022). "It is therefore critical to better understand the regulatory functions and molecular processes of NCOA4 in the cancer database in order to develop innovative therapeutic approaches for cancer." (PMID 35756082, 2022). "Cox regression investigation of 33 forms of cancer found that decreased NCOA4 expression in four types of cancer, namely, CHOL, KIRC, LGG, and SARC, results in a shorter disease-free life." (PMID 35756082, 2022). "In terms of OS, the Cox regression analysis of the 33 forms of cancer demonstrated a significant correlation between the NCOA4 expression level and seven types of cancer, namely, ACC, CHOL, COAD, KIRC, LGG, LUAD, and SARC." (PMID 35756082, 2022). "NCOA4 expression and cancer-associated fibroblast infiltration for the PAAD also exhibited a positive link, whereas neutrophils and NCOA4 expression were shown to be positively correlated with BLCA tumors." (PMID 35756082, 2022). "Our work intended to offer a complete characterization of the NCOA4 landscape in 33 different forms of cancer." (PMID 35756082, 2022). "We examined the connection between the NCOA4 expression and the prognosis of patients with pan-cancer using the TCGA database." (PMID 35756082, 2022). "Reduced NCOA4 expression correlates with shorter disease-free survival in four forms of cancer, namely, CHOL, KIRC, LGG, and SARC." (PMID 35756082, 2022). "With the exception of ACC, decreased NCOA4 expression correlates with shorter overall survival in six kinds of cancer." (PMID 35756082, 2022). "In conclusion, our thorough pan-cancer analysis of NCOA4 demonstrated that it was related to a poor prognosis in individuals who had it downregulated." (PMID 35756082, 2022). "The association between NCOA4 expression and DSS was discovered using Cox regression analysis of 33 different forms of cancer." (PMID 35756082, 2022). "Then, we used COAD as the validation cancer in order to investigate the relationship between the level of NCOA4 expression and the result of COAD." (PMID 35756082, 2022). "We examined NCOA4 expression in stage I, II, III, and IV pan-cancer patients to further study the association between NCOA4 expression and clinical features." (PMID 35756082, 2022). "Previous investigations have shown that mutations in NCOA4 play a role in carcinogenesis and increased expression of NCOA4 was seen in various cancer cell lines." (PMID 33804823, 2021). "In conclusion, previous studies have reported that PHKG2, PEBP1 and NCOA4 are positive regulators that promote ferroptosis in some kinds of cancers, whereas the remaining two genes (ACSL3 and CISD1) suppress ferroptosis in cells." (PMID 34115610, 2021). "Studies have demonstrated that autophagy can promote ferroptosis by providing iron via the degradation of ferritin, termed ferritinophagy, in cancer cells, mediated by nuclear receptor coactivator 4 (NCOA4)." (PMID 33292585, 2020).
cancer (continued). "Analysis demonstrated two known cancer genes (NCOA4 and RET) and a further five candidate cancer genes (LLGL1, LRIG1, LYRM9, ST3GAL6, and TMEM199) were within breakpoint‐containing TADs." (PMID 31943436, 2020). "Our preclinical results support the enrollment of NCOA4-RET-positive cancer patients in a clinical trial of alectinib." (PMID 29088743, 2017). "Altered NcoA4 expression has also been demonstrated in other cancers, including ovarian, renal, oral, and colorectal." (PMID 22562579, 2012). "In conclusion, blocking the binding of NCOA4 to FtMt, inactivating NCOA4, and reducing the stability of NCOA4 may protect cancer cells from ferroptosis by preventing ferritinophagy and maintaining the stored iron level." (PMID 40083691, 2025). "From these perspectives, signalling modulation of the NCOA4‐mediator ferritinophagy–ferroptosis axis may generate a hopeful strategy for drug‐resistant cancer cells on account of different sensitivity to ferritinophagy and response to ferroptosis." (PMID 38389491, 2024). "However, the cancer-inhibiting effect of NCOA4 overexpression was severely disrupted by ferroptosis inhibitors." (PMID 38049396, 2023). "On one hand, due to the siderophilic properties of cancer, NCOA4-mediated ferritinophagy may promote the progression of some tumors." (PMID 37065442, 2023). "In most cancers, the signature genes were differentially methylated compared to normal tissue; in particular, genes including as representatives NCOA4, CTSL, MCUB, ANXA5 and ANGPTL2 were usually hypermethylated, while genes including PDE2A and others were usually hypomethylated." (PMID 37660060, 2023). "NCOA4/RET fusion-positive carcinomas were compared with carcinomas harboring other RET fusions." (PMID 37882481, 2023). "Additional factors such as DNA methylation, immune cell infiltration, and NCOA4-interacting proteins may be of assistance in explaining the role of NCOA4 in the development of cancer from a variety of perspectives." (PMID 35756082, 2022). "Additionally, we reported the relationship between the degree of NCOA4 expression and various clinicopathological characteristics, such as age, gender, T stage, N stage, M stage, and overall survival, in pan-cancer types." (PMID 35756082, 2022). "In addition, although the significance of autophagy in cancer is well established and altered NCOA4 expression is reported in various cancer types, the role of ferritinophagy in tumorigenesis is yet to be clearly defined." (PMID 35888733, 2022). "Now, NCOA4 is considered as a key molecule which can promote ferroptosis in various cancers, and other studies revealed that NCOA4 down-regulation could inhibit ferroptosis by eliminating intracellular Fe2+, glutathione and ROS (reactive oxygen species)." (PMID 36552889, 2022). "A molecular mechanism through which NCOA4 may contribute to the oncogenesis of a variety of human malignancies has been elucidated by our extensive and systematic pan-cancer research efforts." (PMID 35756082, 2022). "Protein expressions of HMOX1, HSPB1 and NCOA4 were markedly decreased in cancer tissues." (PMID 33996565, 2021). "NCOA4 was gradually considered as a key molecule promoting ferroptosis in various cancer cells and mounting studies displayed that NCOA4 depletion can inhibit ferroptosis by eliminating the accumulation of intracellular free iron, glutathione production and reactive oxygen species (ROS)." (PMID 33402128, 2021). "The mRNA expression level of NCOA4 was analyzed in various cancer types." (PMID 33402128, 2021). "Inhibiting nuclear receptor coactivator 4 (NCOA4)-mediated ferritinophagy, a type of selective autophagy for the degradation of ferritin by lysosomes, increases iron storage and limits ferroptosis in cancer cells." (PMID 33268902, 2021). "Among the genes located in these regions, ETV1, CCDC6, and NCOA4 are known cancer critical genes." (PMID 32580154, 2020).
cancer (continued). "We propose that NCOA4 is instead dysregulated at the protein level as a result of altered HERC2 E3 ubiquitin ligase activity; indeed, HERC2 is mutated up to 20% in various cancers (obtained from cBioportal)." (PMID 29435183, 2018). "Notably, NCOA4 exhibited relevance with pathways concerning allograft rejection and NOD-like receptor signaling, while CP was associated with complement and coagulation cascades, focal adhesion, and pathways in cancer." (PMID 38887322, 2024). "Additionally, abnormal DNA methylation (hyper- or hypomethylation) may affect NCOA4 gene expression and consequently cancer processes." (PMID 35756082, 2022). "RET gene fusions have been reported as driver genes for various types of cancer, including thyroid, lung, intestine, pancreas, and breast, and fusions such as CCDC6-RET, NCOA4-RET, and KIF5B-RET are known to be frequently seen." (PMID 40647546, 2025). "To date, there are at least three pathways that mediate ferroptosis in cancer cells: system Xc-/GSH/GPX4, FSP1/CoQ10/NAD(P)H, and ATG5/ATG7/NCOA4." (PMID 36009223, 2022). "GLS2, FBXL5, NCOA4, and SAT1 proteins have also been repeatedly reported as therapeutic targets in cancer and have been used in multi-angle evaluation systems for preclinical investigations." (PMID 36009223, 2022). "To date, many related pathways have been found to mediate ferroptosis in cancer cells, including system Xc-/GSH/GPX4, FSP1/CoQ10/NAD(P)H, and ATG5/ATG7/NCOA4 pathways, which are considered potential therapeutic targets, especially for the treatment of cancers." (PMID 36009223, 2022). "Our study lays the foundation for more comprehensive experimental study (in vitro, in vivo) on modulating the cell death drug targets FANCD2, NCOA4 (COAD), IKBKB, (GBM), and RHOA (GBM and SCLC), to improve the therapeutic avenues in cancer treatment." (PMID 33670487, 2021). "The Cancer Genome Atlas (TCGA) data analysis showed that BCAT2 expression correlated with cancer grade and the expression of ferroptosis markers (GPX4 and NCOA4) in HCC." (PMID 33097833, 2021). "We observed that CDK9 and BRD4 inhibition reduced butyrate-triggered NCOA4 expression, decreased Erastin, RSL3 and butyrate-induced cell death; in contrast, BRD4 inhibition by JQ1 triggered ferritinophagy and ferroptosis in cancer cells." (PMID 33298848, 2020). "A total of 10 genes that were disrupted or within breakpoint‐associated TAD structures were classified as known (FHIT, FLCN, NCOA4, and RET) or candidate cancer genes (LLGL1, LRIG1, LYRM9, RASGEF1A, ST3GAL6, and TMEM199)." (PMID 31943436, 2020). "Importantly, we screened and identified hyperoside (HYP) as a new USP18 enzyme activity inhibitor, which sensitizes cancer cells to existing targeted therapies (sorafenib and regorafenib) by inhibiting USP18 and following deISGylation of NCOA4." (PMID 40514377, 2025). "Here, we focus on clarifying the new discovers of NCOA4 and FTH1 in cancer." (PMID 34858857, 2021). "Our study further confirms a role for NCOA4 in GBM pathophysiology, which might help us further understand the pathogenesis of GBM and develop therapies based on the induction of ferroptois to treat cancer." (PMID 33420375, 2021).
infection (15 papers, 2012 to 2026). The state of being infected such as from the introduction of a foreign agent such as serum, vaccine, antigenic substance or organism. "Following aerosol infection with Mtb (H37Rv), the bacterial loads in the lungs of Ncoa4–/– mice were significantly reduced compared with those in Ncoa4+/+ mice, 4 and 8 weeks after infection." (PMID 37066876, 2023). "Heme oxygenase-1 (HO-1) and nuclear receptor co-activator 4 (NCOA4) involved in converting bound iron into free iron were upregulated after TgCtwh3 infection." (PMID 37651502, 2023). "Next, we detected protein expression related to iron metabolism using Western blot analysis, and the results showed that the expression of TfR1, HO-1, and NCOA4 was upregulated in HT-22 cells 24 h after TgCtwh3 infection." (PMID 37651502, 2023). "The repression of NCOA4 by iron overload and infection is expected to support the cellular capacity to safely retain iron in its chemically inert form and thereby protect cells against potential oxidative stress and microbial burden by intracellular pathogens." (PMID 36290647, 2022). "Infection of previously COPZ1 silenced U87MG cells with a lentiviral construct expressing COPZ1 (OE-COPZ1) resulted in lower expression of NCOA4." (PMID 33420375, 2021). "In order to begin to validate such prediction, co-expression of miRNA-146b and NCOA4 within the colon and differential expression of NCOA4 with increasing doses of infection was assessed by RT-PCR." (PMID 23071818, 2012). "Our computational simulation predicts an upregulation of miR-146b, and IL-17 and a down-regulation of NCOA4 and PPARγ in colons of mice after infection with C. difficile." (PMID 23071818, 2012). "However, the mechanism of NCOA4 in various infections needs to be clarified to precisely target the treatment of infectious diseases." (PMID 38961066, 2024). "TfR1 and NCOA4, which were upregulated after infection recovered to normal levels following DFP." (PMID 37651502, 2023). "We speculate that the NCOA4-dependent mechanism plays a more prominent role in the early stages of Mtb infection than in the later phases of the infection." (PMID 37066876, 2023). "Additionally, NCOA4, targeting ferritin to autolysomal degradation to release iron, was significantly downregulated after infection with SARS-CoV-2." (PMID 35181867, 2022). "Western blotting demonstrated that the levels of NCOA4 and TFRC were upregulated after 24 h infection compared to controls, indicating that ASFV infection facilitated NCOA4-mediated ferritinophagy." (PMID 40548711, 2025). "NCOA4 was mainly localized to the nucleus and cytoplasm, and nuclear localization signals of NCOA4 were reduced toward the cytoplasm and cytosol by transfection of PR8 HA in HEK293T cells or infection with PR8 H1N1 virus in A549 cells." (PMID 39159143, 2024). "Consistently, the Nrf2/HO-1 and ferritin/NCOA-4 axes (controlling iron release) and GPX4 expression level all recovered at 24 h post-infection." (PMID 35265210, 2022). "After infection with TgCtwh3, the TfR1 responsible for iron intake in the cells is decreased; the bound iron stored in FTH1 and heme is released, respectively, by NCOA4 and HO-1, Additionally, the Fpn responsible for iron exclusion in the cells is downregulated." (PMID 37651502, 2023). "Therefore, a direct intervention targeting intracellular iron, NCOA4, or STING will impact normal cellular functions, such as the response to infection, the maintenance of iron metabolic balance, and enzyme activity." (PMID 35902564, 2022).